STAT2 (signal transducer and activator of transcription 2)
Description:
Signal transducer and activator of transcription that mediates signaling by type I interferons (IFN-alpha and IFN-beta). Following type I IFN binding to cell surface receptors, Jak kinases (TYK2 and JAK1) are activated, leading to tyrosine phosphorylation of STAT1 and STAT2. The phosphorylated STATs dimerize, associate with IRF9/ISGF3G to form a complex termed ISGF3 transcription factor, that enters the nucleus. ISGF3 binds to the IFN stimulated response element (ISRE) to activate the transcription of interferon stimulated genes, which drive the cell in an antiviral state. In addition, also has a negative feedback regulatory role in the type I interferon signaling by recruiting USP18 to the type I IFN receptor subunit IFNAR2 thereby mitigating the response to type I IFNs. Acts as a regulator of mitochondrial fission by modulating the phosphorylation of DNM1L at 'Ser-616' and 'Ser-637' which activate and inactivate the GTPase activity of DNM1L respectively.
Synonyms: STAT113; IMD44; ISGF-3; P113; PTORCH3
Tractability: Antibody: its Gene Ontology location is reachable by antibodies, with high confidence. PROTAC: UniProt records ubiquitination sites on it; ubiquitination databases record sites on it; its protein half-life has been measured.
Target class: Transcription factor
Gene: Protein-coding gene on chromosome 12 (56,341,597 to 56,360,274, reverse strand). Ensembl gene ENSG00000170581.
Subcellular location: Cytoplasm; Nucleus
Subcellular location (Human Protein Atlas): Cytosol; Mid piece; Plasma membrane; Principal piece
Pathways (Reactome):
Disease: Dengue virus activates/modulates innate and adaptive immune responses; Evasion by RSV of host interferon responses; Potential therapeutics for SARS; SARS-CoV-2 activates/modulates innate and adaptive immune responses
Immune System: Interferon alpha/beta signaling; Interleukin-20 family signaling; Regulation of IFNA/IFNB signaling
Gene Ontology:
Molecular function: DNA-binding transcription factor activity; DNA-binding transcription factor activity, RNA polymerase II-specific; identical protein binding; protein binding; ubiquitin-like protein ligase binding; RNA polymerase II cis-regulatory region sequence-specific DNA binding; DNA binding
Biological process: cell surface receptor signaling pathway via JAK-STAT; defense response to virus; negative regulation of type I interferon-mediated signaling pathway; positive regulation of transcription by RNA polymerase II; regulation of mitochondrial fission; regulation of protein phosphorylation; type I interferon-mediated signaling pathway; defense response; regulation of cell population proliferation; regulation of transcription by RNA polymerase II; response to peptide hormone; regulation of DNA-templated transcription; signal transduction
Cellular component: cytoplasm; cytosol; ISGF3 complex; nucleus; chromatin; nucleoplasm; RNA polymerase II transcription regulator complex
Genetic constraint (gnomAD): Loss-of-function variants: 51 observed, 129.64 expected, observed/expected ratio (o/e) 0.39, 90% interval 0.31 to 0.5. The upper end of that interval is the gene's LOEUF score, 0.5, which puts it in group 2 of 6, group 1 being the genes least tolerant of losing a copy. Missense variants: 736 observed, 1,062.1 expected, observed/expected ratio (o/e) 0.69, 90% interval 0.65 to 0.74. Synonymous variants: 351 observed, 418.59 expected, observed/expected ratio (o/e) 0.84, 90% interval 0.77 to 0.92.
Homologues: Orthologues: chimpanzee STAT2 (99% identical), macaque STAT2 (97% identical), dog STAT2 (86% identical), pig STAT2 (86% identical), guinea pig STAT2 (78% identical), rat Stat2 (74% identical), mouse Stat2 (69% identical), tropical clawed frog stat2 (39% identical), zebrafish stat2 (35% identical), Caenorhabditis elegans sta-1 (17% identical), Caenorhabditis elegans sta-2 (14% identical). Paralogues in human: STAT1 (37% identical), STAT4 (36% identical), STAT3 (35% identical), STAT5B (24% identical), STAT5A (24% identical), STAT6 (21% identical).
Diseases named in the same sentence as STAT2 in open-access papers:
STAT2 is named in the same sentence as 203 diseases in open-access papers, as found by Europe PMC text mining. Sharing a sentence is not in itself a finding about the gene and the disease. The quoted sentences say what the papers report.
viral infection (108 papers, 2009 to 2026). "It is noteworthy to mention that individuals born with a STAT2 deficiency have susceptibility to viral infections in early childhood, and those who live into adulthood have reduced severity of infections over time." (PMID 41440237, 2025). "Another class of mutations observed in STAT2 results in loss of protein expression, with STAT2 deficiency causing a primary immunodeficiency and susceptibility to severe viral diseases." (PMID 36753016, 2023). "The sample size is too limited to draw definitive conclusions on the nature and range of viral infections that cause life-threatening disease in STAT2 deficiency." (PMID 36976641, 2023). "Our results illustrated that PK-15 Ifnar1 k/o and PK-15 Stat2 k/o cells were susceptible to HIV-1–based reporter virus infection upon IFNβ treatment." (PMID 37939052, 2023). "In conclusion, STAT2 deficiency underlies severe viral diseases characterized by excessive inflammation due to impaired responses to type I IFN in the initial phase of infection." (PMID 36976641, 2023). "Susceptibility to severe natural viral diseases was noted in 43% of STAT2-deficient patients (10/23)." (PMID 36976641, 2023). "Complete STAT2 deficiency can result in a primary immune deficiency and life-threatening viral disease." (PMID 36753016, 2023). "The incomplete penetrance of life-threatening viral diseases in patients with STAT2 deficiency accounts for 15 of the 23 patients being still alive at ages of 3 to 38 years (median: 11 years)." (PMID 36976641, 2023). "While EGFR inhibition by gefitinib did not impact STAT1, it was interestingly able to rescue the otherwise decreased levels of STAT2 phosphorylation caused by vanadate/virus infection." (PMID 35572196, 2022). "STAT2 plays a key role in mediating antiviral immunity, as STAT2-/- mice exhibit increased susceptibility to viral infection and impaired response to type I IFN." (PMID 36148221, 2022). "Among these identified genes, H2-T23, H2-T24, Ifi1, Irf7, and Stat2 were involved in other virus infections, such as those caused by chikungunya virus, Duvenhage virus, and Zika virus." (PMID 34585989, 2021). "While STAT2 deficiency is associated with susceptibility to viral infection, monogenic type I interferonopathies result in upregulation of STAT2 activity and IFN-1 signaling." (PMID 34258050, 2021). "The relevance of STAT2 is further underlined by the finding that humans suffering from loss-of-function mutations in STAT2 exhibit a pronounced susceptibility toward viral infections, including those with attenuated vaccine strains (24, –, 27)." (PMID 29743368, 2018). "STAT2-knockout mice have severe susceptibility to viral infection, and STAT2 is a binding target for measles, a possible culprit in these patients." (PMID 26122121, 2015). "In two children presenting with severe neurological deterioration following viral infection we identified a novel homozygous STAT2 mutation, c.1836 C>A (p.Cys612Ter), using whole exome sequencing." (PMID 26122121, 2015). "Additionally, patients harboring clinically asymptomatic STAT2 mutations were reported to exhibit severe neurological deterioration following viral infection, which was attributed to STAT2 deficiency and which impeded mitochondrial fission." (PMID 39655955, 2025). "Next, we examined whether Ifnar1 k/o or Stat2 k/o augments the susceptibility of PK-15 cells to viral infection in the presence of IFNβ." (PMID 37939052, 2023). "The phenotype of STAT1 and STAT2 deficiency is in part reflected in mice, in that both Stat1–/– and Stat2–/– mice display increased susceptibility to viral infection with increased mortality and indications of inflammation, although formal comparisons are challenging." (PMID 36976641, 2023).
viral infection (continued). "It remains possible that patients with JAK1 deficiency retain relatively normal viral susceptibility in specific cell types in vivo as result of other antiviral mechanism, as has been suggested for patients with complete STAT2 deficiency who also have surprisingly mild viral infections." (PMID 36159783, 2022). "Autosomal recessive STAT2 deficiency results in heightened susceptibility to severe and/or recurrent viral disease, whereas homozygous missense substitution of the STAT2-R148 residue is associated with severe type I interferonopathy due to loss of STAT2 negative regulation." (PMID 34448086, 2021). "In part, this may be due to concerns that use of IFNγ during acute viral disease might exacerbate the hyperinflammatory state that can accompany viral disease in STAT2 deficiency." (PMID 34448086, 2021). "In addition to susceptibility to LAV vaccines, which serves as a “red flag” for defects of IFN-I/III immunity, STAT2-deficient patients also experience increased susceptibility to naturally acquired viral disease." (PMID 34448086, 2021). "However, the effect of the Stat2 loss of function on the ability to resist to a viral infection depends on the type of virus." (PMID 31142600, 2019). "However, if the viral cytopathology was mainly linked to the induction of Stat2-dependent ISGs, we would have observed a more pronounced alteration of the effect of viral infection in GS2 cells in comparison with EC cells." (PMID 31142600, 2019). "Reported cases of STAT2 deficiency are always connected with a background of viral infections." (PMID 29892288, 2018). "The JAK proteins are phosphorylated upon binding of type I IFNs to IFN-α receptor 1 (IFNAR1) and IFNAR2, which then activate transcription factors such as STAT1 and STAT2 to induce transcription of ISGs that respond to viral infections." (PMID 40130878, 2025). "This discovery enhances our understanding of the intricate relationship between STAT2, mitochondrial function, and viral infection." (PMID 39655955, 2025). "Upon viral infection, STAT2 translocates to mitochondria, where it is targeted for degradation by the viral degradasome formed by viral proteins and MAVS." (PMID 39655955, 2025). "Collectively, these data suggest that SVA 3Cpro is responsible for cleaving STAT1 and STAT2 in the virus infection context." (PMID 38869319, 2024). "Endogenous STAT1 and STAT2 were precipitated with SVA 3Cpro in the viral infection context, consistent with the results observed in the overexpression assay." (PMID 38869319, 2024). "In this study, we reveal that SVA 3Cpro suppresses the IFN-induced response by cleaving and degrading STAT1 and STAT2; this observation was confirmed in the context of virus infection." (PMID 38869319, 2024). "Owing to the critical role of HCST and STAT2 in the inflammatory response, we further explored the potential mechanism regulated by these two hub genes after virus infection in myocardial cells." (PMID 38025532, 2023). "To exclude the possible role of the type III IFN-mediated antiviral response by viral infection, we knocked down STAT2 to abolish the type III IFN signaling pathway in A549-sg-IFNAR1 cells." (PMID 37327222, 2023). "Both STAT2- and STAT1-deficient mice are more vulnerable to viral infections, however, unsurprisingly, the effect is more pronounced for STAT1-deficient mice as they also cannot respond to type II interferons, reviewed by Meyts & Casanova." (PMID 37669278, 2023). "Both cells transfected with mutant STAT2 alleles and the patients’ cells displayed impaired expression of IFN-stimulated genes and impaired control of in vitro viral infections." (PMID 36976641, 2023). "In summary, our results revealed an important role of STAT2 phosphorylation at the early stage of viral infection." (PMID 36148221, 2022). "STAT2 is an important transcription factor activated by interferons (IFNs) upon viral infection and plays a key role in antiviral responses." (PMID 36148221, 2022).
viral infection (continued). "The binding of NS5 to STAT2 suppresses the downstream interferon responses that help the viral infection." (PMID 35223554, 2022). "Enriched KEGG and Reactome terms include genes involved in IFN signaling, viral infection, and adaptive immunity, while there were several enriched transcription factor motifs, including Stat2, IRFs, and RelA." (PMID 35578269, 2022). "Altogether, the data are consistent with a model in which CLKs contribute to temperature-controlled Stat2 expression, which, at elevated temperature, increases expression of ISGs and further antiviral genes to increase the defense against viral infection." (PMID 35713540, 2022). "Similar to other members of the STAT family, STAT2 plays an important role in host defense against viral infections." (PMID 36148221, 2022). "This prompted us to test for interactions of vIRF-1 with other members of the STAT family, specifically STAT1 and STAT2, as mediators of innate immune signaling and therefore of central importance to regulation of viral infection and replication." (PMID 35776779, 2022). "As previously shown, fibroblast monolayers from patients with complete STAT2 deficiency supported the formation of large plaques (infected cells) of PIV5 and PIV5VΔC, demonstrating uncontrolled viral infection resulting from failure of the IFN-α response." (PMID 36159783, 2022). "To further investigate kinases involved in STAT2 activation at the early stage of viral infection, we constructed CDK9 or MAPK12 knockdown A549 cells using specific shRNAs, respectively." (PMID 36148221, 2022). "LOF mutations in STAT1 and TYK2 increase susceptibility to bacterial and viral infections, while LOF in STAT2 increases the incidence of viral infections and LOF in STAT4 increases the incidence of fungal infections." (PMID 35337171, 2022). "In this study, we showed that viral infection and DNA damage are two stresses inducing an episodic surge of A3A expression using two distinct mechanisms orchestrated by the transcription factors STAT2 and p65." (PMID 34389714, 2021). "Accordingly, virus infection causes higher expression of IFNa2, IFNb1, OAS1, and STAT2 in Nlrx1−/− mice when compared to wild-type mice." (PMID 33525590, 2021). "Hyperinflammatory features such as prolonged fevers requiring hospitalization in response to viral infection, unprovoked sepsis-like presentations, and even HLH have been noted in approximately two-thirds of patients with AR STAT2 deficiency." (PMID 34448086, 2021). "In response to a viral infection, STAT2 translocates to the mitochondria, and likely attenuates the cell’s anti-viral response and suppresses innate immunity." (PMID 33426505, 2020). "Since STAT2 plays an important role in host defense against viral infection and carcinogenesis, we provide a brief review of STAT2 activity regulation and discuss the novel role of STAT2 activity regulation in carcinogenesis, especially melanoma." (PMID 32973222, 2020). "Of note, background levels of pY-STAT1 and total levels of STAT1 and STAT2 were observed as being increased following virus infection in several analyses." (PMID 32272626, 2020). "The transcription factor STAT2 takes center stage in the type I IFN response as it is essential to mediate an antiviral state that helps the host clear a viral infection." (PMID 31009517, 2019). "In models of viral infection, STAT2 signaling is exploited by measles virus and choriomeningitis virus to interfere with dendritic cell (DC) development and expansion." (PMID 31009517, 2019). "In the meantime, as an effort to develop novel animal models of viral infection, we have developed a signal transducer and activator of transcription 2 (STAT2) gene knockout (KO) golden Syrian hamster." (PMID 30678320, 2019). "For more than a quarter century, we have known that STAT1 and STAT2 are essential for the classic host immune defense system against viral infections known as the type 1 interferon response." (PMID 27780205, 2016).
viral infection (continued). "Type I interferons (IFNα and IFNβ) activate STAT1 and STAT2 proteins via phosphorylation and are required for early control of a viral infection." (PMID 27178303, 2016). "Hereby, we report findings with a new Syrian hamster strain (STAT2 KO hamsters), in which the Type I interferon pathway, an important part of the innate immune response to virus infection, is disrupted." (PMID 26291525, 2015). "We chose these genes because of their roles in viral infection (STAT2), cardiovascular function (KCNQ1) or being the most widely used genomic locus for transgene integration (PPP1R12C)." (PMID 25299451, 2014). "When NS5 is expressed during virus infection, during replicon replication, or from a plasmid encoding NS1 through 5, cellular STAT2 levels diminish." (PMID 22590678, 2012). "Indeed, a study by some of us in using STAT2 knockout Syrian hamsters (STAT2−/−) has demonstrated that STAT2 signalling plays a dual role in viral infections, both aggravating lung injury and also limiting the systemic spread of SARS-CoV-2." (PMID 40122829, 2025). "STAT2 is a transcription factor essential for the signal transduction pathway of type I interferons (IFNs), which are known as the classic host immune defense system against viral infections." (PMID 38762176, 2024). "However, most studies on STAT2 have focused on host defense against viral infection or oncogenic effects, and few reports have demonstrated the involvement of STAT2 in neuropathic pain." (PMID 36744245, 2023). "The most significant roles of STAT1 relate to its ability to facilitate appropriate cellular changes in response to the entire family of IFN proteins, while the involvement of STAT2 is limited to responses downstream of IFNα and IFNβ, particularly mediating immunity to viral infections." (PMID 38255152, 2023). "A study suggests a score including the ERK2 SNPs, rs2266966 and rs5999521, binding to many transcription factors, such as STAT2, which is involved in the defence response to virus; in fact, knockout mice for STAT 2 are more predisposed to have viral infections." (PMID 37239131, 2023). "Furthermore, it was observed that the early activation of STAT2 during viral infection was mainly regulated by the RIG-I/MAVS-dependent pathway." (PMID 36148221, 2022). "Since MAPK12 is a serine/threonine kinase, it is possible that MAPK12 might modulate the activation of an unidentified tyrosine kinase that is responsible for the phosphorylation of STAT2 at Y690 during the early stage of viral infection." (PMID 36148221, 2022). "Therefore, the data suggest that the phosphorylation of STAT2 Y690 at the early stage of viral infection was mainly regulated through the RIG-I/MAVS signaling." (PMID 36148221, 2022). "In addition, precise mechanisms underlying the regulation of MAPK12 activation and phosphorylation of STAT2 by MAPK12 during viral infection deserve further investigation." (PMID 36148221, 2022). "Since STAT2 Y690 could be phosphorylated at the early stage of viral infection, we asked whether the phosphorylation of STAT2 had any effect on IAV replication." (PMID 36148221, 2022). "Problems handling other LAV vaccines (such as the yellow fever vaccine) have not been reported in STAT2 deficiency, but would be expected by analogy to homozygous IFNAR1 deficiency or IFN-I autoantibodies." (PMID 34448086, 2021). "Although the majority of STAT2 studies in the last few decades have focused on interferon (IFN)-α/β (IFNα/β) signaling pathway-mediated host defense against viral infections, recent studies have revealed that STAT2 also plays an important role in human cancer development." (PMID 32973222, 2020). "The viral infection causes the phosphorylation and translocation of IRF7 to the nucleus and as a result the induction of expression of type-I interferons which in turn activates IRF7 transcription through STAT2." (PMID 31665046, 2019).